CDK4 (cyclin dependent kinase 4)
Diseases named in the same sentence as CDK4 in open-access papers (continued):
Sharing a sentence is not in itself a finding about the gene and the disease.
sarcoma (continued). "The findings from this single-arm, phase II trial suggest that palbociclib has activity in advanced sarcomas other than WD/DD-LPS selected by RNA expression of CDK4 and CDKN2A, showing a promising median PFS and OS in a heavily pretreated population." (PMID 37875500, 2023). "Cyclin-dependent kinases 4 and 6 (CDK4/6) inhibitors demonstrated activity in terms of progression-free survival (PFS) in advanced dedifferentiated liposarcoma (DD-LPS), a sarcoma with CDK4 amplification." (PMID 37875500, 2023). "A fine-tuned selection with a 4-biomarker set is recommended based on this trial, for future use of CDK4/6 inhibitors in sarcoma patients." (PMID 37875500, 2023). "Recent studies have shown CDK4/6 inhibitors such as palbociclib, which can make sarcoma cells sensitive to Wee1 kinase inhibition through reversible cell cycle arrest." (PMID 37089080, 2023). "Future therapeutic strategies combining CDK4/6 inhibitors with other compounds seem worthwhile and also deserve to be explored in the sarcoma field." (PMID 37875500, 2023). "Compared to its homolog, CDK4 favors mesenchymal tissues (including leukemias and sarcomas), and epithelial tumours (i.e., various malignancies), and some sarcomas tend to express more CDK4." (PMID 36768557, 2023). "Despite the fact that a valuable predictive biomarker selection for CDK4/6 inhibition is challenging, the selected biomarkers with RNA overexpression of CDK4 and no overexpression of CDKN2A seem adequate for future studies with CDK4/6 inhibitors in sarcomas." (PMID 37875500, 2023). "Palbociclib was active in a variety of sarcoma subtypes, selected by CDK4/CDKN2A, and deserves further investigation in the sarcoma context." (PMID 37875500, 2023). "Gene amplifications are frequently present in sarcomas and were also identified in this study, namely CDK4 and MDM2 in 10.0% and 7.0% of cases, respectively." (PMID 36430703, 2022). "Palbociclib in combination with other agents effectively arrested the growth of all sarcoma PDOX tumors, showing that a CDK4/6 inhibitor is active against sarcoma." (PMID 36003796, 2022). "The sarcoma PDOX model presents an opportunity to discover candidate unproven therapeutics for sarcoma, including the CDK4/6 inhibitor palbociclib." (PMID 36003796, 2022). "We also demonstrate a mechanistic insight using CDK4/6i and oncolytic adenovirus in this innovative combination therapy approach for the treatment of bladder cancer and sarcoma cells." (PMID 35948546, 2022). "Due to their tumor-inhibiting effect in multiple preclinical studies, CDK4/6 inhibitors have become the central component in phase 1 and 2 trials for various sarcoma subtypes." (PMID 35884441, 2022). "In this study, we evaluate the antitumor effect of XVir-N-31 and adenovirus wild type (ADWT) in combination with different CDK4/6i in vitro in a panel of bladder cancer and sarcoma cell lines and in murine xenograft sarcoma mouse models." (PMID 35948546, 2022). "In some cases, although CDK4 was positive in both the cartilage and sarcoma portions, the cartilage portion showed focal positive expression, while the sarcoma portions showed mainly diffuse expression." (PMID 34631758, 2021). "Five genes are expressed only in this type of sarcoma: PIK3CA, MDM2, HMGA2, EGFR, CDK, CDK4, while CDKN2A is implicated in angiosarcomas and undifferentiated pleomorphic sarcomas only." (PMID 34359782, 2021). "Detection of MDM2 (and/or CDK4) amplification serves to distinguish DDL from other undifferentiated sarcomas." (PMID 34362013, 2021). "Based on impressive anti-tumor activities in pre-clinical studies, CDK4/6 inhibitors have become a central component of current phase 1 and 2 clinical trials for various types of sarcoma." (PMID 32344731, 2020).
sarcoma (continued). "Given the widespread presence of CDK4‐amplification/high expression and CDKN2A loss across sarcomas subtypes, CDK4 inhibitors such as palbociclib are also a promising strategy in RB‐positive tumors." (PMID 33047515, 2020). "Currently, there is a multi-center phase 2 trial of palbociclib monotherapy in Spain for patients who have advanced sarcomas with elevated expression of CDK4 (NCT03242382)." (PMID 32344731, 2020). "Previous studies on Rhabdomyosarcoma show that CDK4 is essential for sarcoma cell survival and growth, in which knockdown of CDK4 lead to abrogate proliferation of Rhabdomyosarcoma." (PMID 30808351, 2019). "Phase II multicenter trial of palbociclib in second line of advanced sarcomas with CDK4 overexpression." (PMID 30631751, 2018). "Considering the absence of information available about the patients’ follow-up and clinical outcomes of the synovial sarcoma TMA, we correlated the CDK4 expression levels to the clinical prognosis of the various types of sarcoma TMA." (PMID 29670090, 2018). "In our study, synovial sarcoma TMAs determined by IHC showed that CDK4 expression was observed in most of the tested sarcoma tissue samples." (PMID 29670090, 2018). "These indications show that CDK4-targeted therapies in sarcomas can be used across CKS types; continuous monitoring for disease recurrence is required." (PMID 30598078, 2018). "Altogether, these results verify the expression of CDK4 in synovial sarcomas and highlight its important role in sarcomas, including synovial sarcoma." (PMID 29670090, 2018). "According to the TCGA sarcoma data, CDK4 amplification and recurrence showed co-occurrence (P = 1.60e-05, Chi-square test)." (PMID 30598078, 2018). "The results of this analysis indicated that these sarcomas had very few gene mutations and a high frequency of amplifications of not only MDM2 and CDK4 but also other genes." (PMID 28099935, 2017). "Here, the authors generate a cancer cell line from a paediatric patient with a rare undifferentiated sarcoma and through functional genomics and chemical screens identified CDK4 and XPO1 as potential therapeutic targets in this cancer." (PMID 27329820, 2016). "We have found that sarcoma tumors with combined high levels of CDK4 mRNA and low levels of p16INK4a, respond to palbociclib (a CDK4 inhibitor) in a panel of PDX models in vivo, irrespective of the tumor type." (PMID 27563810, 2016). "Cell lines from several sarcoma subtypes with defined molecular backgrounds, such as GIST with KIT mutations and dedifferentiated LPS with MDM2 and CDK4 amplification, were treated with selinexor to investigate potential mechanisms of action." (PMID 26918731, 2016). "In the present work, we explore the efficacy of CDK4 inhibition using palbociclib (PD0332991), a highly selective inhibitor of CDK4/6, in a panel of sarcoma cell lines and sarcoma tumor xenografts (PDXs)." (PMID 26528855, 2015). "Our data reinforce previously published data on the suitability of CDK4 inhibition for cell cycle-dependent tumors and support the performance of new molecularly directed clinical trials for other types of sarcoma." (PMID 26528855, 2015). "In summary, our data support the efficacy of CDK4 inhibitors against sarcomas displaying increased CDK4 levels, particularly fibrosarcomas and MPNST." (PMID 26528855, 2015). "To study the effect of CDK4 inhibition in sarcoma, a tumor type with few therapeutic approaches, we examined the effects of the CDK4 inhibitor palbociclib on sarcoma cell lines and PDX models." (PMID 26528855, 2015).
sarcoma (continued). "In the present work, we tested the suitability of CDK4 inhibition using palbociclib for sarcomas and explored possible markers of efficacy that are independent of the sarcoma tumor type." (PMID 26528855, 2015). "In vivo sarcoma xenografts harboring CDK4 amplification also show significant responses to flavopiridol either as a single agent or in combination with doxorubicin." (PMID 26528855, 2015). "To study the functional relationship between the CDK4 levels and the cellular response to palbociclib, we overexpressed wild type CDK4 cDNA in 2 different sarcoma cell lines, AW and AX." (PMID 26528855, 2015). "To explore the effect of CDK4 inhibition, we used a panel of 10 low-passaged sarcoma cell lines generated directly from patient samples and 2 commercial cell lines of heterogeneous origin and different molecular karyotypes." (PMID 26528855, 2015). "Since our study is limited to one case only, further studies are required to elucidate the antitumor efficacy of crizotinib and the CDK4 inhibitor in sarcomas in the context of clinical trials." (PMID 24406431, 2014). "Detection of amplification of MDM2 and/or CDK4 is potentially informative with respect to this sarcoma type." (PMID 24216705, 2013). "SDUS may be susceptible to EZH2 or CDK4/6 inhibition, and early evidence suggests that ERBB2/3-mutated S100/SOX10-positive sarcomas may benefit from HER2-targeted therapy." (PMID 41463261, 2025). "In our study, CDK4 expression was predominant in biphasic sarcoma samples." (PMID 41155410, 2025). "CDK4/6 inhibitors in sarcomas exhibited multifaceted results." (PMID 41514647, 2025). "Importantly, genes found in this region have been associated with tumorigenesis and include sarcoma amplified sequence (SAS), cyclin-dependent kinase 4 (CDK4), and glioma-associated oncogene homolog (GLI)." (PMID 40867318, 2025). "The herein applied OV XVir-N-31 is soon to be tested in a combination therapy with CDK4/6 inhibition in phase 1 clinical trials for pediatric sarcoma, hence the assessment of additional combinations including XVir-N-31 and other immune activating agents is obvious." (PMID 38357194, 2024). "In such cases, this potential indication could be extended to any type of sarcoma, with alterations in the regulation of CDK4 and CDK6." (PMID 38275873, 2024). "In other sarcomas with entirely different histologies, such as epithelioid hemangioendothelioma or high-grade chondrosarcomas, genetic alterations affecting CDK4 and CDK6 have also been described." (PMID 38275873, 2024). "Although the use of CDK4/6 inhibitors across sarcomas remains limited, specific subtypes could be sensitive to this therapeutic strategy as either monotherapy or combination therapy." (PMID 38434982, 2024). "CDK4 overexpression is by far more common than amplification in sarcomas and it might be a rational target for CDK inhibitors." (PMID 37875500, 2023). "A significant correlation between median PFS, OS, and the overexpression level of CDK4 indicates that CDK4/6 inhibitors may have a role in the treatment of advanced sarcoma patients." (PMID 37875500, 2023). "The results of our study also suggest that the CDK4 IHC protein score may be an adequate biomarker for CDK4 inhibitor activity in sarcoma, in addition to CDK4 mRNA expression." (PMID 37875500, 2023). "Summary of efficacy of CDK4/6 inhibitors in the sarcoma PDOX studies." (PMID 36003796, 2022). "Furthermore, 38% of these uterine BCOR sarcomas showed amplification of CDK4, whereas 45% enhanced MDM2." (PMID 35884441, 2022). "Sarcoma patients carrying these aberrations may be suitable candidates for clinical trials of CDK4 inhibitors." (PMID 31528332, 2019). "Thus, our model showed that co-expression of MDM2 and CDK4 in transformed human BMSCs increases the tendency of high-grade sarcoma with a DDLPS-like morphology." (PMID 31160689, 2019).
sarcoma (continued). "Our results suggest that the co-overexpression of MDM2 and CDK4, along with multiple genetic factors, increases the tendency for high-grade sarcoma with a DDLPS-like morphology in transformed human BMSCs by accelerating their growth and migration and blocking their adipogenic potential." (PMID 31160689, 2019). "A knockdown of CDK4 in fusion-gene positive rhabdomyosarcoma cells has also been shown to abrogate transformation and proliferation via G1-phase cell-cycle arrest, demonstrating that CDK4 is also essential for sarcoma cell survival and growth." (PMID 29670090, 2018). "Moreover, co-expression of murine double minute 2 (MDM2) and cyclin-dependent kinase 4 (CDK4) along with a dedifferentiated subtype of high-grade sarcoma was seen." (PMID 30115116, 2018). "Furthermore, the CDK4 amp group was enriched in both the CKSs and TCGA sarcomas in patients with recurrence." (PMID 30598078, 2018). "CDK4 amplification is actionable for differentiated sarcomas (OncoKB level 2)." (PMID 30442178, 2018). "CDK4 was significantly amplified in the CKSs and TCGA sarcoma patients." (PMID 30598078, 2018). "Given the co-amplification of the MDM2 and CDK4 genes in sarcoma, we sought to test whether the combined inhibition of both gene products might synergistically eliminate cancer cells." (PMID 30206211, 2018). "However, we show that inhibitors of MDM2 and CDK4 antagonize each other in their cytotoxicity towards sarcoma cells." (PMID 30206211, 2018). "Therefore, it appears that palbociclib can be applied to other sarcoma types, especially those expressing high CDK4 levels and low p16INK4a levels." (PMID 26528855, 2015). "Activating CDK4 mutations are less frequently reported in tumors than CDK4 gene amplification, and not reported in sarcoma tumors." (PMID 26528855, 2015). "However, high levels of p16INK4a exist also in some tumors with wild type pRb as in those carrying HPV (E7 protein targets pRb), or that over express MDM2, commonly co-amplified with CDK4 in sarcomas." (PMID 26528855, 2015). "However, CDK4 overexpression is by far more common than amplification in sarcomas and it might be a rational target for CDK inhibitors." (PMID 37875500, 2023). "Authors show here that when combined, CDK4/6 inhibitors deplete Retinoblastoma protein levels, which leads to more efficient virus replication and an increase in oncolytic virus-producing cancer cells and thus to efficient anti-tumor response in mouse xenograft sarcoma models." (PMID 35948546, 2022). "TMA analysis showed that the overexpression of CDK4 was related to higher clinical stages and higher TNM grades in synovial sarcomas and this correlated with a poorer patient prognosis in various sarcomas, indicating that CDK4 might be necessary for tumor metastasis." (PMID 29670090, 2018). "Of note, CDK4 amplification in sarcoma cells was not susceptible to the PDGFRA target drug." (PMID 30598078, 2018). "The interplay between CDK4 and MYC forms a pivotal oncogenic axis that drives the progression of various cancers, including sarcomas." (PMID 40076599, 2025). "The availability of CDK4 and CDK6 cyclin inhibitor drugs (anti-CDK4 and anti-CDK6) makes them excellent choices for targeting sarcomas with these genetic alterations in the form of deletions or amplifications." (PMID 38275873, 2024). "The standard procedure to identify a sarcoma includes the detection of this amplification through fluorescence in situ hybridization (FISH) and/or MDM2/CDK4 immunohistochemistry." (PMID 39687824, 2024). "The second condition was simplicity: any overexpression of CDK4 and equal or underexpression of CDKN2A for the tested sarcoma against the RNA pool, accomplished with the biomarker selection." (PMID 37875500, 2023).
sarcoma (continued). "Indeed, presence of multiple alterations in different steps of cell cycle regulation might provide primary/secondary resistance mechanisms to CDK inhibition; moreover, when present, CDK4 amplification is the main oncogenic driver of only a subset of CDK4-amplified sarcomas." (PMID 36741019, 2023). "We extracted the expression profiles of four sarcoma-related tumor biomarkers, MDM2, CDK4, CD34, and TLE1, from the cohorts TCGA-SARC and GSE21050 and analyzed their expression profile in each IMS." (PMID 36153483, 2022). "At the second recurrence, the pathological diagnosis after biopsy was of sarcoma with MDM2(+) and CDK4(+) immunohistochemical staining results." (PMID 35096429, 2022). "In this subtype of sarcoma, CDKN2A firmly connects to MDM2, CCND1, PIK3CA, CDK4, CBX7, and less firmly to EGFR, and IL-6." (PMID 34359782, 2021). "Dedifferentiated liposarcoma (DDLPS) is a highly malignant sarcoma characterized by the co-amplification of MDM2 and CDK4." (PMID 34834427, 2021). "Overexpression of CDK4 correlates with higher clinical stages and higher TNM grades in synovial sarcomas and poor survival outcomes of sarcoma patients." (PMID 29670090, 2018). "To investigate the differences between CDK4 amp and CS groups, we identified the PDGFRA target drug responses in nine sarcoma cell lines." (PMID 30598078, 2018). "Various types of sarcoma TMA specimens were also assessed for CDK expression and localization, demonstrating varying degrees of CDK4 staining in the cell nucleus." (PMID 29670090, 2018). "CDK4 was amplified in 21.4% of CKS patients and in 18.7% of TCGA sarcoma patients (P = 0.83, t-test)." (PMID 30598078, 2018). "The identification of CDK4 and XPO1 provide evidence to support testing of these agents in other paediatric undifferentiated sarcomas." (PMID 27329820, 2016). "An increased sensitivity to palbociclib was observed in cells overexpressing wild type CDK4, whereas the overexpression of the CDK4R24C mutant increased the resistance of both sarcoma cell lines to palbociclib." (PMID 26528855, 2015). "Although it was originally thought that CDK4 is co-amplified with other Chr 12q13-15 genes, such as MDM2, it appears that different genes within this region are amplified dependent on the sarcoma subtype." (PMID 26528855, 2015). "To explore the effect of CDK4 inhibition in vivo, we used PDX models produced from a panel of different types of sarcoma." (PMID 26528855, 2015). "Of this last group, four were undifferentiated sarcomas and immunostaining for MDM2 and/or CDK4 was positive in three." (PMID 24216705, 2013). "Altered regions included known targets, such as CDK4 (cyclin-dependent kinase 4) and SAS (sarcoma amplified sequence), as well as MDM2 (mouse double minute 2 homolog), for 12q14.1 and 12q15 amplifications, respectively." (PMID 20444257, 2010). "Hence, a plethora of alterations beyond CDK4/6 genes emerges as highly relevant for sarcoma pathobiology, providing several potential actionable targets at various steps of the CDKN2A-CCND-CDK4-RB axis." (PMID 36741019, 2023). "Currently, the focus is on defining sarcomas based on their histologic subtype, molecular profile and genetic changes, rather than their anatomic origin, which will aid the development of novel therapies, like MDM2 and CDK4/6 inhibitors." (PMID 37888062, 2023). "Principally, MDM2 and CDK4 examination allows differentiation of WDLPS from benign adipose tumors while in DDLPS, MDM2 and CDK4 evaluation help to exclude poorly differentiated sarcomas." (PMID 36230502, 2022). "Hyperactive CDK4 has been reported in epithelial malignancies in the endocrine tissues and mucosa while CDK6 activation was reported in certain mesenchymal tumors such as sarcomas and leukemias [reviewed in 1]." (PMID 36051751, 2022). "Although many sarcoma types have alterations in the CDK4/6 pathway, so far, no CDK4/6 inhibitor is approved for sarcoma treatment." (PMID 36003796, 2022).